RNF126 (ring finger protein 126)
Diseases named in the same sentence as RNF126 in open-access papers (continued):
Sharing a sentence is not in itself a finding about the gene and the disease.
tumor (10 papers, 2016 to 2025). "IR treatment resulted in the weight of tumor reduction rates of 59.42% and 84.29% in the Rnf126 WT group and Rnf126 KO group, respectively." (PMID 36563124, 2023). "We applied the signature to The Cancer Genome Atlas (TCGA) to determine RNF126 was highly expressed in the tumor tissues and constructed RNF126-related network modules through weighted gene coexpression network analysis (WGCNA)." (PMID 36539893, 2022). "For example, an increase in PDK1 levels by exogenous PDK1 expression in the cells suppressed colony formation and tumor growth, similar to the effects of RNF126 depletion." (PMID 27462466, 2016). "To confirm the role of RNF126 in tumor development, we first investigated the results of cell proliferation changes from the knockdown of RNF126." (PMID 27227488, 2016). "Despite the modest effect of RNF126-KD on cell growth in monolayers, marked suppression of colony formation in soft agar was observed, and, accordingly, tumor formation in mice was also reduced." (PMID 27462466, 2016). "Although it was difficult to completely exclude the involvement of other target proteins in our assays, PDKs appeared to be the major targets of RNF126 involved in cell growth regulation during colony formation in soft agar and tumor formation in mice." (PMID 27462466, 2016). "The results showed that RNF126 was upregulated in tumor samples compared with normal samples." (PMID 36539893, 2022). "Furthermore, PTEN knockdown restored cell proliferation, metastasis, and tumor formation of BCa cells inhibited by RNF126 silencing in vitro and in vivo." (PMID 33664240, 2021). "The transplantation tumor model of nude mice was used to evaluate the tumorigenecity of RNF126." (PMID 27227488, 2016). "Depletion of RNF126 also attenuated tumor growth in mice in a PDK-dependent manner." (PMID 27462466, 2016). "The transplantation tumor model of nude mice was used to evaluate the tumorigenicity of RNF126." (PMID 27227488, 2016). "The knockdown of RNF126 attenuated the tumor progression in vivo." (PMID 27227488, 2016). "This biphasic inhibitory effect of PDK1 and RNF126 may indicate that growth and survival of tumor cells are highly sensitive to fine-tuning of the PDK1-mediated metabolic pathway." (PMID 27462466, 2016). "A similar effect was observed with A549 cells, as RNF126-KD decreased tumor volume by ~40%." (PMID 27462466, 2016). "Thus, RNF126 depletion had a greater impact on colony formation in vitro and tumor formation in vivo than in cultured monolayers in vitro." (PMID 27462466, 2016). "Furthermore, RNF126 regulated the tumor volume on mice model." (PMID 27227488, 2016). "However, RNF126 may target other proteins responsible for the effect of RNF126 on tumor growth in mice." (PMID 27462466, 2016). "Dihydroartemisinin, a potent antimalarial agent, is proven to inhibit RNF126 expression and enhance radiotherapy sensitization on mouse model with a TNBC tumor in the brain, exhibiting high potential in clinical application." (PMID 36563124, 2023). "RNF126-depleted MDA-MB-231 cells were implanted subcutaneously into immunodeficient mice and tumor growth was monitored." (PMID 27462466, 2016). "Mice bearing a subcutaneous xenograft derived from MCF7 or MDA-MB-231 cells with or without RNF126 knockdown showed significantly reduced tumor growth after RNF126 knockdown." (PMID 36539893, 2022). "We investigated whether AZD6738 would exhibit anti-tumor efficacy in xenografts with or without RNF126 knockdown model." (PMID 36539893, 2022). "Similarly, cells expressing exogenous PDK1 developed into tumors with ~70% smaller volumes than observed with the corresponding control cells at day 25, and PDK1 overexpression in RNF126-depleted cells did not decrease the tumor volumes further." (PMID 27462466, 2016). "Enhanced expression of PDK1 in RNF126-depleted cells did not further suppress tumor growth." (PMID 27462466, 2016).
RNF126 also shares sentences with these, for which no sentence is quoted: chronic lymphocytic leukemia (1 paper); lung carcinoma (1); lymph node metastasis (1); metastatic disease (1); oral cancer (1); serous ovarian cancer (1); stomach cancer (1); X-linked intellectual disability (1).